CCND1 (cyclin D1)
Diseases named in the same sentence as CCND1 in open-access papers (continued):
Sharing a sentence is not in itself a finding about the gene and the disease.
glioblastoma (continued). "Inhibition at G1 phase and reduction in cyclin D1 expression level indicate that glioblastoma cells are undergoing differentiation on TCE treatment." (PMID 24205314, 2013). "In another study the NSAID aspirin induced apoptosis by the inhibition of cyclin D1 and Bcl-2 in the A172 glioblastoma cell line." (PMID 23231886, 2012). "LPP3 depletion reduced β-catenin and CYCLIN-D1 proteins, thereby impairing U87 and U118 glioblastoma cell proliferation and migration." (PMID 21569306, 2011). "Our results revealed that treatment with hUCBSC notonly decreased the expression of cyclin D1 but also that of β-catenin in U251and 5310 cells as compared to the reported data in U251 glioblastoma cells." (PMID 21455311, 2011). "We found that LLL12 inhibited the transcription of the STAT3 downstream target genes, cyclin D1, survivin, Bcl-2, and Bcl-xL in medulloblastoma and glioblastoma cell lines." (PMID 21526200, 2011). "Representative images of the xenograft experiment are shown and suggest that LPP3-depletion in glioblastoma tumors reduces tumor growth by dampening β-catenin and CYCLIN-D1 activity." (PMID 21569306, 2011). "The GSK3β inhibitor AR-A014418 effectively counteracted the effects of GAD1 knockdown, suppressing the enhanced proliferation, cell cycle progression, and invasion of glioblastoma cells, while also reducing the expression of p-GSK3β, β-catenin, Cyclin D1, and MMP9." (PMID 41844572, 2026). "We also evaluated BATF2 and cyclin D1 expression within glioblastoma multiforme (GBM) patient samples to assess if a similar relationship may exist in disease." (PMID 40945729, 2025). "The development of drugs that selectively suppress the activity of cyclin D1 may potentially block or control this altered activity, perhaps offering promising prospects for the treatment of glioblastoma." (PMID 39366930, 2024). "Glioblastoma cells treated with a combination of EPZ015666 and PP242 resulted in a significant loss of cell viability, an increase in the number of apoptotic cells and a reduction in the expression of c-MYC and cyclin D1." (PMID 39703687, 2024). "Furthermore, BTBD10 overexpression inhibits proliferation, induces G0/G1 arrest, and promotes apoptosis in human glioblastoma cells by downregulating cyclin D1- and Akt-dependent signaling pathways." (PMID 36045715, 2022). "Furthermore, another work conducted on U87MG cells has shown that curcumin determines the promotion of cell cycle arrest in glioblastoma cells by downregulation of cyclin D1, together with upregulation of p21." (PMID 35328780, 2022). "Furthermore, BTBD10 overexpression inhibits proliferation, induces G0/G1 arrest, and promotes apoptosis in human glioblastoma cells by downregulating cyclin D1 and attenuating Akt signaling." (PMID 36045715, 2022). "Meanwhile, downregulation of GSK-3β, p-GSK-3β, β-catenin and their downstream, c-Myc and cyclin D1 using the Chr-A treatment indicates that Chr-A may exert anti-glioblastoma activity by downregulating the Akt/GSK-3β/β-catenin pathway." (PMID 36234681, 2022). "MiR-302 directly represses cyclin D1 and suppresses the proliferation of glioblastoma cells." (PMID 34113619, 2021). "Furthermore, NDRG1 overexpression inhibited glioblastoma cell growth by decreasing expression of cyclin D1/E and CDK 2/4 in a cell‐cycle signalling pathway." (PMID 34965023, 2021). "Taken together, we speculated that HMGN5 in glioblastoma cells could regulate Bcl-2, Bax, Cyclin D1, p21, MMP-2, and MMP-9 to play an oncogenic role partly via the PI3K/AKT pathway." (PMID 32596388, 2020).
glioblastoma (continued). "Moreover, let-7b downregulation contributes to cisplatin resistance in glioblastoma cell lines promoting tumor cell growth through the upregulation of cyclin D1." (PMID 31575060, 2019). "Through suppression of several oncogenes including p-AKT, EZH2, XIAP, CDK6, cyclin-D1 and cyclin-D2, overexpression of miR-340 inhibits cancer cell proliferation, migration and invasion, induces apoptosis and autophagy in glioblastoma and miR-340 is a marker for glioblastoma diagnosis and prognosis." (PMID 27036021, 2016). "Cyclin D1 plays an important role in cell migration promoting the migratory and invasive capacity of macrophages, fibroblasts, breast epithelial cells and human glioblastoma cells." (PMID 26689991, 2016). "Reconstitution of let-7b re-sensitized glioblastoma cells to cisplatin by abrogating cyclin D1." (PMID 25946136, 2015). "Our results also indicated that down-regulation of Let-7b was correlated with cisplatin resistance in glioblastoma cells, and Let-7b could attenuate cyclin D1 expression then dampen chemoresistance of U251R cells to cisplatin." (PMID 23806108, 2013). "Recent studies suggested the USP10/CCND1 pathway as a potential therapeutic target for glioblastoma (GBM) patients." (PMID 38953023, 2024). "In glioblastoma multiforme (GBM) patients, high levels of DLX2 have been associated with a poor survival outlook, and knockdown of DLX2 in GBM cells reduced cyclin D1 expression." (PMID 34203994, 2021). "miR-340 was found to specifically target the 3' UTRs of CDK6, cyclin-D1, and cyclin-D2, leading to the arrest of glioblastoma multiforme (GBM) cells in the G0/G1 cell cycle phase 42." (PMID 33390846, 2021). "Based on the first major studies, more recently authors demonstrated that Cyclin D1 plays a role in the dissemination of glioblastoma (GBM) in vivo." (PMID 33317149, 2020). "It has been reported that miR-93 and miR-193 act to decrease cyclin D1 and induce quiescence in glioblastoma multiforme (GBM), which leads to a lower percentage of cycling cells." (PMID 31467934, 2019). "Alterations of post-translational expression of HSP70 by the stemness marker nestin has been shown to regulate tumor growth and invasiveness in glioblastoma via cyclin D1 and therefore an inhibition of both HSP70 and nestin might improve outcome of glioblastoma patients." (PMID 26771644, 2016). "Therefore, the ability to suppress the malignant phenotype by decreasing CCND1 expression may provide a new approach for gene therapy in patients with glioblastoma." (PMID 26317630, 2015). "Inhibition of the G1 regulating genes CDK4 or Cyclin D1 in glioblastoma cells may lead to the restoration of the G1 checkpoint and subsequent glial differentiation as the cyclin D1-cdk4 axis is the primary gateway through which mitogenic information is channelled." (PMID 24205314, 2013). "Therefore, cyclin D1 down-regulation induced by restoration of Let-7 in tumors might be a novel therapeutic strategy for cisplatin-resistant glioblastoma treatment." (PMID 23806108, 2013). "PBMCs from glioblastoma patients exhibited increased expression of the regulatory genes SOCS1, SOCS3, and PTEN, while CCND1 was downregulated." (PMID 41898348, 2026). "Collectively, these results suggest that GAD1 inhibits the expression of Cyclin D1 and MMP9 via the p-GSK3β/β-catenin pathway, thereby impeding glioblastoma progression." (PMID 41844572, 2026). "Intriguingly, upon EGF receptor activation, PKM2 binds histone H3 and phosphorylates histone H3 at T11, resulting in the acetylation of histone H3 at K9 to activate CCND1 and MYC expression in glioblastoma cells." (PMID 40059196, 2025). "In glioblastoma, the intricate interaction between phosphorylation and methylation of HNRNP A1 results in modified activity of cyclin D1." (PMID 39366930, 2024). "In glioblastoma (GBM), one study showed that Cyclin D1 (CCND1) is involved in cell cycle control and promotes tumor progression." (PMID 36248971, 2022).
glioblastoma (continued). "Furthermore, decreased expression of Akt-affected GSK-3β and their downstream proteins including β-catenin, c-Myc and cyclin D1 in U251 and U87-MG cells after Chr-A treatment for 48 h implied that Chr-A may exert an anti-glioblastoma action via the Akt/GSK-3β/β-catenin signaling pathway in vitro." (PMID 36234681, 2022). "The same effect has been observed with Stt in BTIC glioblastoma cells; activation of STAT-3 induces upregulation of c-Myc, Cyclin D1 and Bcl-xL and protects against apoptosis to promote cell survival and proliferation." (PMID 35703345, 2022). "The expression of CCND1 is decreased in HEK293T and the glioblastoma cell line U343 after overexpression of EYFP-tagged AATK wt in comparison to EYFP-tagged AATK KD or EYFP empty." (PMID 35902728, 2022). "We here show that SFRP2-overexpression decreases CCNE1, CCND1 and CCNB1, and at the same time decreases SOX2 protein and overall cell proliferation in glioblastoma cells." (PMID 34021259, 2021). "The KD enhanced the anti-tumor efficacy of Bev in a glioblastoma intracranial implantation mouse model, based on lowest levels of microvascular density (CD31) and cellular proliferation markers (Ki-67 and CCND1) in KD + Bev tumors compared to the other groups." (PMID 33420169, 2021). "In human glioblastoma derive cells, P4 increased the expression of EGFR and cyclin D1 through its PR and the recruitment of steroid receptor coactivator-1 (SRC-1)." (PMID 33752729, 2021). "Next, we determined that Presenilin1 inhibited the growth and proliferation of glioblastoma cells by downregulating CDK6, C-myc and Cyclin D1 to arrest the cell cycle at the G1/S phase." (PMID 32046730, 2020). "By upregulating miR-145 expression, cyclin-D1 and SOX2 are downregulated, leading to G0/G1 arrest in patient-derived glioblastoma spheres (PDGS) resulting in anchorage-independent growth inhibition." (PMID 32906592, 2020). "The role of miR-149 was explored in glioblastoma where it was found to inhibit the expression of MMP-2, p-AKT1, proliferating cell nuclear antigen (PCNA), cyclin D1, as well as proliferation and invasion in U251 cells." (PMID 24670365, 2014). "After overexpression of CDKN2A in glioblastoma cell lines T98G, U87-MG and SW1783 MG, the expression of cyclin D1 was decreased." (PMID 21843312, 2011). "In addition, we examined the relationship of BATF2 and cyclin D1 in patient-derived glioblastoma samples and found that elevated levels of BATF2 had a corresponding decrease in cyclin D1." (PMID 40945729, 2025). "In both glioblastoma and cancer stem cells, downregulation of NUAK2 by micro-RNA could inhibit PI3k; thus, leading to downregulation of cyclin D1 and upregulation of p27." (PMID 39071701, 2024). "In glioblastoma cells, high PTK2 expression can increase the expression of CCND1 and CCNE, reduce the expression of CDKN1B (p27Kip1) and p21Waf1, and enhance the activity of CDK4, thereby promoting the G1/S phase transformation of glioblastoma cells." (PMID 36770809, 2023). "The choice to investigate these genes (Cyclin D1, Caspase 3, p62, and LC3B) was suggested on the basis of literature, in which analogue pathways were investigated for RIP proteins, such as saporin-6, tested on glioblastoma cell lines, GL15 and U87MG." (PMID 34678977, 2021). "Similarly, in the treatment of glioblastoma (GBM) and colorectal cancer using the multi-attenuated HSV-1 mutant G47D, TSA improved the antitumor effects synergistically, with cyclin D1 blockade and VEGF inhibition." (PMID 32992948, 2020). "The mechanism by which CREB regulates glioblastoma tumor cell proliferation involves activities downstream from both the MAPK and PI3K pathways that then modulate the expression of three key cell cycle factors, cyclin B1, cyclin D1 and PCNA." (PMID 27926502, 2017). "Interestingly, the knockdown of SMARCB1 in glioblastoma and medulloblastoma generated little effect on the LIN28B levels and the expression of CCND1 and CDKN1C." (PMID 27095948, 2016).
glioblastoma (continued). "miR-340 inhibits glioblastoma cell proliferation by suppressing CDK6, cyclin-D1 and cyclin-D241." (PMID 27686215, 2016). "Given that β-catenin and CYCLIN-D1 are known regulators of tumor cell proliferation and migration, we examined the relationship between LPP3 expression and β-catenin and CYCLIN-D1 in U87 and U118 glioblastoma cell proliferation and migration." (PMID 21569306, 2011). "In glioblastoma, PRMT5 activity conferred therapeutic resistance to mammalian target of rapamycin (mTOR) inhibitors by mediating the methylation of heterogeneous nuclear ribonucleoprotein 1 (hnRNP A1) to promote the translation of cyclin D1 and c-MYC, leading to drug resistance." (PMID 39703687, 2024). "Western blot analysis of patient-derived glioblastoma cells NULU treated with increasing concentrations of quinoin showed a dose-independent reduction of Cyclin D1, while the ZAR cell line exhibited a significant reduction of Cyclin D1 at the maximal concentration used (250 nM)." (PMID 34678977, 2021). "Therefore, in this glioblastoma model, DYRK1 inhibition may favour the arrested subpopulation with high cyclin D1 but also high p21 levels over a population with increased cell proliferation." (PMID 34708541, 2021). "Consistently, it did not alter the mRNA levels of cyclin D1 (CCND1) and MYC1 pertinent to cell cycle progression, suggesting that ODZ10117 affects the viability of glioblastoma cells, but not proliferation." (PMID 32183406, 2020). "However, MGH57 (grade IV glioblastoma) revealed a relatively small subpopulation of malignant cells that do not express OLIG1, OLIG2, DLL1, CCND1, and IGFBPL1, but express ALDOC and ATP1A2." (PMID 33607293, 2021).
myeloma (132 papers, 2006 to 2025). "It is important to remember that plasma cell myeloma, blastic variant can be cyclin D1 positive (30-40%)." (PMID 39099606, 2024). "HCP5/miR-128-3p/PLAGL2 signaling was associated with an increased risk of multiple myeloma through altered Wnt/-catenin/cyclin D1 signaling." (PMID 36793341, 2022). "Previous studies have found that in myeloma, the dysregulation of CCND1 is associated with oncogenic event in patients, but further functional studies are needed to validate." (PMID 34917133, 2021). "MCL and multiple myeloma/plasmacytoma with 11q13 abnormalities typically express Cyclin D1 transcript variants with the longer 5′-untranslated regions (5′ UTRs)." (PMID 34442137, 2021). "A hallmark of a large fraction of multiple myelomas is a chromosomal translocation t(11:14) in which the CCND1 locus is joined to the immunoglobulin locus (IGH locus)." (PMID 25799187, 2015). "Also in this more stringent comparison, MCL samples consistently carry more than twice as many non-coding variants in the CCND1 locus as multiple myeloma samples." (PMID 35145272, 2022). "Furthermore, we characterize a novel distal interaction upstream of the Cyclin D1 gene which provides mechanistic evidence for the abundant overexpression of Cyclin D1 occurring in multiple myeloma cells harboring a pathogenic translocation event." (PMID 25799187, 2015). "In light of the fact that cyclin D1 dysregulation, when associated with multiple myeloma, is an early event in oncogenesis, this disparity argues substantively against clonal identity between the 2 tumors; it is likely that they arose as two independent primary neoplasms separated in space and time." (PMID 24715915, 2014). "On the other hand, hyperdiploid myeloma, which constitutes the other half of the disease, is usually associated with trisomies of odd-numbered chromosomes (except chr13), in particular trisomies of chr11 leads to direct upregulation of cyclin D1." (PMID 24330858, 2013). "Mutation of at least one out of five genes (cyclin D1, C-MAF, FGFR3/MMSET, cyclin D3 and MAFB) seems to be a consistent finding in plasma cell myeloma which requires about three such rate limiting steps on average to manifest clinically." (PMID 40720480, 2025). "Cyclin D1 expression is a hallmark of MCL; however, it can occasionally be observed in plasma cell neoplasms, including plasma cell myeloma and SEP, contributing to diagnostic confusion." (PMID 40821198, 2025). "In a case report, a patient with rapid progression and poor prognosis was identified as having double‐hit multiple myeloma, characterized by both IgH/CCND1 and IgH/MYC translocations." (PMID 40859868, 2025). "Among hematolymphoid tumors, BCL1 is found to be overexpressed in > 90% of MCL cases and about 40% of plasma cell myelomas, both of which are caused by a translocation which juxtaposes the immunoglobulin heavy chain (IGH) gene to the CCND1 gene." (PMID 38914869, 2024). "Notch activation by osteocytes increases CYCLIN D1 expression and enhances the proliferation of myeloma cells." (PMID 37174109, 2023). "Genetic knockdown of NOTCH3 in myeloma cells prevented the increase in CYCLIN D1 expression and proliferation induced by osteocytes." (PMID 37174109, 2023). "Myeloma cells highly expressed well-known driver genes, including CCND1, NDS2/MMSET, CCND3 and pathway analysis showed prominent upregulations of multiple biological processes and pathways in myeloma cells compared with nPCs." (PMID 36717896, 2023). "For example, in multiple myeloma cells, cyclin D1 promotes hexokinase 2 expression, a regulator of glycolysis in these cells." (PMID 38152849, 2023). "Cyclin D1 expression can also be seen in other lymphoid malignancies, for example, pleomorphic and blastoid variants of MCL, plasma cell myelomas, and cases of chronic lymphocytic leukemia." (PMID 36312606, 2022).